CDX2 (caudal type homeobox 2)
Diseases named in the same sentence as CDX2 in open-access papers (continued):
Sharing a sentence is not in itself a finding about the gene and the disease.
adenocarcinoma (continued). "Importantly, these findings are not consistent with previous studies, which demonstrated that CDX2 levels are reduced in colonic polyps of Apc+/– mutant mice and in adenocarcinomas of mice treated with azoxymethane, which is a chemical carcinogen." (PMID 33755595, 2021). "Similar to the NE component, CDX2 was also positive in the adenocarcinoma component in two cases." (PMID 32408525, 2020). "Cdx2 overexpression in the gastric mucosa of transgenic mice using the parietal cell-specific H+/K+-ATPase subunit b promoter resulted in gastric intestinal-type metaplasia that spontaneously developed into adenocarcinomas." (PMID 31739541, 2019). "In addition to its reactivity in almost all colorectal adenocarcinomas, CDX2 immunopositivity has been detected in considerable numbers in several adenocarcinomas from different sites such as the gastrointestinal tract, pancreas, and ovary." (PMID 29721106, 2018). "CDX2 is a highly sensitive and specific marker of adenocarcinomas of intestinal origin." (PMID 28095874, 2017). "CDX2 is a sensitive and specific maker for adenocarcinoma with a colorectal origin." (PMID 27473859, 2016). "Immunostaining was CDX2-positive, indicating adenocarcinoma from the intestinal epithelium." (PMID 27389415, 2016). "CDX2, a master transcriptional regulator of intestinal cell differentiation and survival, has been used as a marker to indicate colorectal lineage in adenocarcinomas of unknown origin." (PMID 24489794, 2014). "Since PDAC is one of most common origin for adenocarcinoma of unknown primary and CDX2 has been widely used to establish the primary site, it is of importance to clarify CDX2 expression in PDAC." (PMID 24489794, 2014). "CDX2 is a fairly specific marker for the gastrointestinal origin of an adenocarcinoma." (PMID 24024058, 2013). "These authors reported that high levels (> 75% positive cells) of CDX2 expression were found almost exclusively in adenocarcinomas of the colorectum, and intermediate levels (26%-75% positive cells) of immunostaining were found in many adenocarcinomas arising elsewhere in the GI tract." (PMID 22268990, 2012). "In addition, the high percentage of negativity for CDX2 of small/large bowel MCs and undifferentiated/rhabdoid carcinomas may aid in their differential diagnosis with poorly differentiated conventional adenocarcinomas, most of which are CDX2‐positive." (PMID 39192803, 2025). "GLI1 binds to the caudal type homeobox 2 (CDX2), responsible for maintaining the intestinal phenotype promoter, activating the site independently of SMO, which supports a non-canonical transition from squamous to columnar epithelium metaplasia in Barrett’s-associated adenocarcinoma cells." (PMID 33494284, 2021). "Moreover, malignant cells were present, consistent with adenocarcinoma (CK7+/CK20-/CDX-2-/CA-125+)." (PMID 29867159, 2018). "However, CDX2 expression may also be positive in adenocarcinomas of the upper gastrointestinal tract and other lesions, including those of the uterine cervix." (PMID 26810414, 2016). "Adenocarcinomas with a colorectal immunophenotype (CK7 -, CK20 +, CDX2 +) fall into this category, and these patients are recommended to receive site-directed therapy targeting the suspected primary origin for better outcomes." (PMID 41561743, 2025). "As expected, xenograft tumors exhibited the typical histology of CRC adenocarcinomas, expressing the proliferation marker KI67 and partially also differentiation markers such as CDX2, particularly following KAT2A knockdown." (PMID 40140561, 2025). "Key immunohistochemical markers, including CK20, CDX2, and TTF‐1, play a pivotal role in distinguishing PEAC from other adenocarcinomas." (PMID 39980580, 2025).
adenocarcinoma (continued). "Immunohistochemical analyses play a crucial role in diagnosing these rare malignancies, with markers such as CDX2, CK20 and CK7 helping to differentiate the adenocarcinoma phenotypes." (PMID 40697355, 2025). "For adenocarcinoma, particularly intestinal type, an immunopanel including CK7, CK20, CDX2, and SATB2 (± PAX8) should be interpreted alongside a directed GI work-up to exclude metastasis." (PMID 41375020, 2025). "For adenocarcinomas, an intestinal-type immunophenotype (CK20/CDX2/SATB2) should prompt GI work-up to exclude metastasis." (PMID 41375020, 2025). "Positive markers for the adenocarcinoma component included CK8/18, CDX2, and C-erB-2, whereas positive markers for the neuroendocrine component included chromogranin A, synaptophysin, CD56, and a high Ki-67 index (~40%)." (PMID 40909957, 2025). "Microscopically, they were adenocarcinomas immunoreactive for MOC31, CK20, and CDX2, and their final pathologic diagnosis was adenocarcinoma of colorectal origin." (PMID 38608071, 2024). "The CDX2 and SOX2 expression demonstrated a converse pattern in the metaplasia-dysplasia-adenocarcinoma progression sequence in both esophageal and gastric cases." (PMID 36994101, 2023). "Panels of immunohistochemistry including MUC1, MUC2, CDX2, CK20 and MUC5AC can help in the classification of adenocarcinomas as intestinal or pancreatobiliary type in a substantial proportion of cases." (PMID 35565398, 2022). "Intestinal-type adenocarcinomas generally express CDX-2, MUC2 and CD10, whereas the gastric-type adenocarcinomas express MUC5AC and MUC6." (PMID 35565398, 2022). "Chromogranin A, synaptophysin, CD56, CK35BH11 were used for the neuroendocrine lineage and AE1/AE2, CDX2, CK7, CK20 to confirm the existence of adenocarcinoma cells." (PMID 34201925, 2021). "In our study, an immunohistochemistry panel with specific markers was performed in all MiNEN cases, evidencing the presence of both neuroendocrine components (chromogranin A, synaptophysin, CD56, CK35BH11) and adenocarcinoma cells (AE1/AE2, CDX2, CK7, CK20)." (PMID 34201925, 2021). "He underwent biopsy of one liver lesion, and pathology demonstrated poorly differentiated adenocarcinoma with focal neuroendocrine differentiation (CK7+, CDX2+, synaptophysin/chromogranin+, CK20−, TTF1−, napsin−) consistent with pancreatic or biliary origin." (PMID 31371345, 2019). "Biopsy of the hepatic lesions showed adenocarcinoma positive for pan-cytokeratin, CMA5.2, villin, and CDX2." (PMID 28811946, 2017). "Five remaining loci, CDH13, CDX2, OPCML, SFRP1 and TWIST1 were designated as “late” loci; significantly elevated DNA hypermethylation was only detected in adenocarcinoma, as compared with AIS." (PMID 21731750, 2011). "Immunohistochemistry consistently demonstrated positivity for squamous markers (p63, p40, CK5/6) with relative absence of adenocarcinoma-associated markers (CK20, CDX2)." (PMID 41756316, 2026). "Immunostaining showed only rare cytokeratin 20 (CK20) positive cells, which were negative for CK7 and caudal type homeobox 2 (CDX2), suggesting the absence of an epithelial component and thus making the diagnosis of adenocarcinoma unlikely." (PMID 39077246, 2024). "Its immunoprofile is similar to that of conventional adenocarcinoma (CK20+, CDX2+, MUC2+)." (PMID 31340478, 2019). "Biopsy of the large mediastinal showed poorly differentiated adenocarcinoma that stained positive for CK7 but negative for CDX2, TTF‐1, NapsinA, and CK 20, consistent with an ampullary origin." (PMID 31102323, 2019). "Taken together, CDX2 is not helpful in the differential diagnosis of adenocarcinomas in the urinary bladder." (PMID 29721106, 2018). "In present study, the immunohistochemical analysis showed positive staining in the CDX-2, CK-20 and villin, while the adenocarcinoma part was negative for CK-7, ER and HER2." (PMID 25297496, 2014).
adenocarcinoma (continued). "The histological examination of the right hemicolectomy specimen revealed an adenocarcinoma in caecum staining positive for Cytokeratin 7 and Carcinoembryonic antigen and negative for Cytokeratin 20, CDX2 and Estrogen receptor." (PMID 18471290, 2008). "As it was shown previously, ITAC and adenocarcinomas of the intestinal tract show to a great extent morphological similarities, as well as overlapping immunohistochemical expression profile, including typically positive staining for CK20, CDX2, villin, MUC2 and SATB2." (PMID 35015192, 2022). "The adenocarcinoma component and the intestinal metaplastic epithelium in the gallbladder were both positive for CDX2, but the neuroendocrine component in hilar lymph nodes was negative for CDX2." (PMID 27842605, 2016). "Immunostains showed that the neoplastic cells were positive for CDX‐2 and CK20, and negative for CK7, WT‐1, TTF‐1, PAX‐8, and GATA‐3, supporting the diagnosis of adenocarcinoma with intestinal differentiation." (PMID 40028792, 2025). "Biopsy of the transverse colon tumor confirmed a poorly differentiated adenocarcinoma, which was positive for CK-7 and TTF-1, very focally positive for napsin A, but negative for CK-20 and CDX-2." (PMID 39292398, 2024). "Adenocarcinomas express carcinoembryonic antigen (CEA), CA 19-9, cytokeratins 7, 19, AE 1/3, CK7, CK20, and caudal type homeobox 2 in the non-neuroendocrine component." (PMID 38655135, 2024). "Biopsy revealed a poorly differentiated adenocarcinoma positive for CK-7 and TTF-1, very focally positive for napsin A, and negative for CK-20 and CDX-2." (PMID 39292398, 2024). "The immunohistochemistry (IHC) profile of positive CDX2 and CK20 and negative PAX8, CK7, ER, and PR suggested a colorectal-type somatic adenocarcinoma arising from the MCT and was staged as IA, after negative endoscopic findings." (PMID 37753035, 2023). "A CT scan-guided liver mass biopsy was performed and demonstrated adenocarcinoma with immunohistochemical staining positive for CK7 and negative for CDX2 and CK20." (PMID 36420295, 2022). "iCCC diagnostic criteria are: (a) composite CCC with conventional adenocarcinoma or presence of adenomatous component, (b) absence of adjacent endometriosis, (c) intestinal immunoprofile (CK20+, CK7−, CEA+, CDX-2+)." (PMID 31340478, 2019). "Microscopically, the hernia sac was diffusely infiltrated by moderately differentiated adenocarcinoma, which was positive for CK7 and pancytokeratin and negative for TTF-1, CK20, PSA, and CDX2." (PMID 30009070, 2018). "Lung biopsy revealed a poorly differentiated adenocarcinoma with immunohistochemistry (IHC) positive for CEA, CK20, CDX2, and negative for CK7, TTF-1, Napsin A, synaptophysin, and chromogranin." (PMID 27171493, 2016). "Immunohistological analysis demonstrated that the adenocarcinoma cells were positive for cytokeratin 20 (CK20) and negative for cytokeratin 7 (CK7) and positive for caudal type homeobox transcription factor 2 (CDX2)." (PMID 27473859, 2016). "CDX2, mCEA, CD56, synaptophysin, NSE and chromogranin can help differentiate it from non-endocrine poorly differentiated adenocarcinoma." (PMID 17803816, 2007). "Furthermore, the histological tumor type was moderately to poorly differentiated adenocarcinoma positive for CK-7 and TTF-1, very focally positive for napsin A, but negative for CK-20 and CDX-2." (PMID 39292398, 2024). "Finally, the differential diagnosis of ITAC from sinonasal nonintestinal adenocarcinomas is supported by immunohistochemistry for CK20, CDX-2, villin and SATB-2 which only stain ITACs." (PMID 28321774, 2017). "The adenocarcinoma component was strongly positive for cytokeratin 7 and pancytokeratin, weakly positive for synaptophysin and CD56, and negative for carbonic anhydrase IX, CD99, CDX2, chromogranin, cytokeratin 20 and smooth muscle actin." (PMID 19523243, 2009).
adenocarcinoma (continued). "The adenocarcinoma component was strongly and diffusely immunoreactive (3+, cytoplasmic staining) for CK7 and pancytokeratin; weakly and focally immunoreactive (1+, cytoplasmic staining) for CD56 and synaptophysin; and negative for CA-IX, CD99, CDX2, chromogranin, CK20 and SMA." (PMID 19523243, 2009).
gastrointestinal tumors (17 papers, 2009 to 2025). "Given the morphological similarities between MPUAP and colorectal cancer, as well as CDX2 positivity (a hallmark of gastrointestinal tumors), our pathologists recommended NGS to further characterize the tumor at the genetic level." (PMID 39902031, 2024). "In the literature, the sensitivity for CDH17 has been reported to be 96–100% for colorectal, 18–57% for pancreatic, 25–90% for gastric, and 39–82% for esophageal AC, and often higher than CDX2 for the upper GI tumors." (PMID 37349623, 2024). "CDX2, commonly expressed in gastrointestinal tumors, has also been identified in tumors with mucinous differentiation across various organs." (PMID 39902031, 2024). "Overexpression of CDX2 is considered a reliable prognostic factor and sensitive biomarker for gastrointestinal tumors." (PMID 37553876, 2023). "CDX2 is a monoclonal antibody to the intestinal-epithelia-specific nuclear transcription factor, and is a relatively new marker for gastrointestinal tumors." (PMID 21689464, 2011). "This panel can include antibodies against antigens commonly expressed by genitourinary or gastrointestinal tumors, such as cytokeratins (CKAE1/AE3, CK7, CK20, CK5/6), p63 (Tumor protein 63), PSA (prostatic specific antigen) or CDX2." (PMID 29110729, 2017). "Our results show that the specific markers of gastrointestinal tumors, including CDX2 and SATB2, were consistently negative in SRCC, while Villin or COX2 had positive expression levels in one case, so this indicator needs to be carefully considered in the differential diagnosis." (PMID 37337182, 2023). "Furthermore, TTF-1, PSA and CDx2 negative IHC excluded epididymal metastases from lung, thyroid, prostate and gastrointestinal tumors, respectively." (PMID 33912469, 2021). "Moreover, negative staining for CDX2 supported the gastric lesion was not primary gastrointestinal tumor." (PMID 27829227, 2016).
infection (16 papers, 2012 to 2025). The state of being infected such as from the introduction of a foreign agent such as serum, vaccine, antigenic substance or organism. "Additionally, our analyses of human and mouse gastric tissues confirmed elevated expression levels, and a positive correlation among TPT1, OCT1, and CDX2 in GIM which are associated with H. pylori SlyD infection." (PMID 39915880, 2025). "The expression of cdx2 was alleviated in infection-III and -IV at all the time points compared to infection-I." (PMID 34585958, 2021). "K20 and SI were induced following combined infection with Cdx2 and HNF1α whereas villin expression was reduced." (PMID 27875772, 2017). "Western blot analysis of CDX2 showed 2.4 fold increase at 8 hr and 2.1 fold increase at 4 hr of infection when compared to untreated." (PMID 25365201, 2014). "In the present study, we generated a polyclonal population of MKN-7, TMK-1, HSC-44PE, and KATO-III cells which express high levels of CDX2 by infection with retroviruses carrying a full-length human CDX2 cDNA." (PMID 23133598, 2012). "However, adult oesophageal explant cultures fail to express any intestinal markers following Cdx2 infection despite the fact that we can obtain efficient Cdx2 expression in the K14-expressing cells in both normal and low calcium culture conditions." (PMID 27875772, 2017). "After selection of infected cells, several clones were recovered, derived from stable infection of stem cells, which grew into organoids expressing Cdx2 that could be passaged indefinitely." (PMID 25500896, 2014). "GM-2 and GM-3 were predominantly associated with columnar epithelial responses and included regulators such as ATF2, CDX2, FOXJ2, and AHR, with infection-induced up-regulation of TFs such as SPI1, ESRRA, RFX1, and RARA." (PMID 41042872, 2025). "Moreover, we noted a decreased expression of cdx2 while comparing infection-III and -IV at 12, 24, and 48 h with infection-II." (PMID 34585958, 2021). "Subsequent infection with Cdx2 induced K20 and SI expression, while HNF1α did not." (PMID 27875772, 2017).
colonic polyps (5 papers, 2017 to 2023). "Collectively, our study shows that the HNF1AA98V variant plus a HFD promotes the formation of colonic polyps by activating β-catenin via decreasing Cdx2 expression." (PMID 37219942, 2023). "CDX2 mutation upregulates colonic polyp number and increases the proliferation of colonic cells, whereas the re-expression of CDX2 inhibits cyclin D1 expression and cell proliferation in human intestinal epithelial crypt cells lacking Cdx2." (PMID 28835570, 2017). "Adenomatous polyposis coli flox mice with a Cdx2-Cre transgene (CPC-APC) develop colonic polyps that contain both dysplastic and malignant tissue." (PMID 37185743, 2023). "As both CDX2 and matriptase have clinical relevance, we suggest that future research might benefit from this link between the transcription factor and the protease/inhibitor system in relation to intestinal disorders." (PMID 30087389, 2018). "In our study, we found that β-catenin levels increased concurrently with its pro-proliferative targets MYC and MMP-7 in the Hnf1A98V polyps, while CDX2 levels were depressed in the colonic polyps but not in the adjacent tissue." (PMID 37219942, 2023).
gastrointestinal disease (2 papers, 2014 to 2021). A disease that occurs in the gastrointestinal system, excluding the hepatobiliary system. "CDX2 is a transcription factor critical for intestinal differentiation being involved in the initiation and maintenance of gastrointestinal diseases." (PMID 24925340, 2014). "Previous research assessing CDX2 has basically focused on gastrointestinal diseases." (PMID 33621200, 2021).
inflammation (2 papers, 2018). Aberrant reaction of the microcirculation characterized by movement of fluid and leukocytes from the blood into extravascular tissues. "The intestine specific transcription factors CDX1 and CDX2 are reportedly triggers for metaplastic transition, with differential expression in normal esophageal mucosa compared to metaplasia and CDX2 expression increases with esophageal inflammation." (PMID 30450163, 2018).
hematological disease (1 paper, 2020). "Mice expressing Cdx2 in HSPCs develop lethal hematological diseases with prominent features of MDS and subsequent transformation into AL." (PMID 32541670, 2020). "Unexpectedly, we observe reduced expression of Hox cluster genes and upregulation of differentiation factors in Cdx2 HSPCs, signifying that non-Hox-mediated pathways drive these hematological diseases." (PMID 32541670, 2020).
CDX2 also shares sentences with these, for which no sentence is quoted: prostate adenocarcinoma (8 papers); colorectal (7); small cell carcinoma (4); small intestine tumors (4); undifferentiated carcinoma (3); adrenal gland tumors (2); breast tumor (2); colon (2); gynecological cancers (2); lymphoma (2); Myelodysplasia (2); paraganglioma (2); thyroid adenocarcinoma (2); thyroid neoplasms (2); acute T-cell leukemia (1); Alpha-thalassemia (1); ampulla of Vater (1); appendiceal neoplasm (1); B-cell neoplasm (1); bile duct tumor (1); bladder (1); bladder transitional cell carcinoma (1); carcinoma in situ (1); carcinosarcoma (1); cardia cancer (1); cervical mucinous adenocarcinoma (1); chordoma (1); choriocarcinoma (1); Chronic colitis (1); chronic kidney disease (1).
A further 82 diseases each share a sentence with CDX2 in 1 paper.